ZNF79 (zinc finger protein 79)
Description:
May be involved in transcriptional regulation.
Synonyms: pT7
Tractability: Antibody: the Human Protein Atlas places it where antibodies can reach. PROTAC: ubiquitination databases record sites on it.
Gene: Protein-coding gene on chromosome 9 (127,424,374 to 127,449,728, forward strand). Ensembl gene ENSG00000196152.
Subcellular location: Nucleus
Subcellular location (Human Protein Atlas): Cytosol; Nucleoplasm; Plasma membrane
Pathways (Reactome):
Gene expression (Transcription): Generic Transcription Pathway
Gene Ontology:
Molecular function: protein binding; DNA-binding transcription factor activity, RNA polymerase II-specific; RNA polymerase II transcription regulatory region sequence-specific DNA binding
Biological process: regulation of transcription by RNA polymerase II; regulation of DNA-templated transcription
Cellular component: nucleus
Genetic constraint (gnomAD): Loss-of-function variants: 13 observed, 18 expected, observed/expected ratio (o/e) 0.72, 90% interval 0.47 to 1.15. The upper end of that interval is the gene's LOEUF score, 1.15, which puts it in group 5 of 6, group 1 being the genes least tolerant of losing a copy. Missense variants: 585 observed, 602.14 expected, observed/expected ratio (o/e) 0.97, 90% interval 0.91 to 1.04. Synonymous variants: 202 observed, 221.77 expected, observed/expected ratio (o/e) 0.91, 90% interval 0.81 to 1.02.
Homologues: Orthologues: macaque ZNF79 (95% identical), chimpanzee ZNF79 (94% identical), pig ZNF79 (89% identical), dog ZNF79 (85% identical). Paralogues in human: ZNF583 (44% identical), ZNF551 (44% identical), ZNF304 (43% identical), ZSCAN20 (43% identical), ZSCAN2 (43% identical), ZNF570 (42% identical), ZNF792 (42% identical), ZNF256 (41% identical), ZNF480 (41% identical), ZNF587B (40% identical), ZNF773 (38% identical), ZNF418 (37% identical), and 26 more.
Diseases named in the same sentence as ZNF79 in open-access papers:
ZNF79 is named in the same sentence as 10 diseases in open-access papers, as found by Europe PMC text mining. Sharing a sentence is not in itself a finding about the gene and the disease. The quoted sentences say what the papers report.
cancer (2 papers, 2023 to 2024). A tumor composed of atypical neoplastic, often pleomorphic cells that invade other tissues. "There are no relevant reports of ZNF79, PRICKLE3, RPAP1, ABHD8, and FBXO33 in cancer, and more research is still needed." (PMID 37274025, 2023).
ZNF79 also shares sentences with these, for which no sentence is quoted: tumor (2 papers); Atrophy (1); breast carcinoma (1); developmental delay (1); infection (1); ovarian carcinoma (1); prostate carcinoma (1); viral encephalitis (1); viral infection (1).